RNASE7 (ribonuclease A family member 7)
Description:
Exhibits a potent RNase activity. Has broad-spectrum antimicrobial activity against many pathogenic microorganisms including uropathogenic E.coli (UPEC), and remarkably potent activity (lethal dose of 90% < 30 nM) against a vancomycin resistant Enterococcus faecium. Causes loss of bacterial membrane integrity. Probably contributes to urinary tract sterility. Bactericidal activity is independent of RNase activity.
Synonyms: RAE1
Tractability: Antibody: UniProt places it where antibodies can reach, with high confidence; its Gene Ontology location is reachable by antibodies, with high confidence; UniProt predicts a signal peptide or a membrane-spanning region.
Gene: Protein-coding gene on chromosome 14 (21,042,316 to 21,044,234, forward strand). Ensembl gene ENSG00000165799.
Subcellular location: Secreted
Pathways (Reactome):
Immune System: Antimicrobial peptides
Gene Ontology:
Molecular function: lipopolysaccharide binding; peptidoglycan binding; protein binding; RNA nuclease activity; nucleic acid binding
Biological process: antibacterial humoral response; antimicrobial humoral immune response mediated by antimicrobial peptide; cytolysis in another organism; defense response to fungus; defense response to Gram-negative bacterium; defense response to Gram-positive bacterium; innate immune response
Cellular component: cytoplasm; extracellular region
Genetic constraint (gnomAD): Loss-of-function variants: 0 observed, 0.16 expected, observed/expected ratio (o/e) 0, 90% interval 0 to 1.88. That is too few expected variants to judge how well the gene tolerates losing a copy. Missense variants: 90 observed, 97.02 expected, observed/expected ratio (o/e) 0.93, 90% interval 0.78 to 1.11. Synonymous variants: 34 observed, 41.6 expected, observed/expected ratio (o/e) 0.82, 90% interval 0.62 to 1.09.
Homologues: Orthologues: chimpanzee RNASE7 (98% identical), macaque RNASE7 (92% identical). Paralogues in human: RNASE8 (77% identical), RNASE6 (52% identical), RNASE2 (41% identical), RNASE3 (40% identical), RNASE1 (35% identical), RNASE4 (34% identical), ANG (28% identical), RNASE10 (24% identical), RNASE9 (22% identical), RNASE13 (22% identical), RNASE12 (19% identical), RNASE11 (17% identical).
Diseases named in the same sentence as RNASE7 in open-access papers:
RNASE7 is named in the same sentence as 43 diseases in open-access papers, as found by Europe PMC text mining. Sharing a sentence is not in itself a finding about the gene and the disease. The quoted sentences say what the papers report.
atopic dermatitis (6 papers, 2016 to 2025). "We have identified RNAse7, the short form of thymic stromal lymphopoietin, and collagen XXIIIα as host proteins that contribute to the susceptibility to eczema herpeticum in patients with atopic dermatitis and modulate HSV-1 infection in human keratinocytes (78, –, 81)." (PMID 39945537, 2025). "RNase 7 (R7) exhibits antimicrobial and immunomodulatory activities and is upregulated in the lesional skin of atopic dermatitis and psoriasis patients." (PMID 40461723, 2025). "In this model, increased mRNA and protein expression of β-defensin 3 and RNase 7 was detected in MS skin, similar to previous reports in skin of individuals with pityriasis versicolor and atopic dermatitis." (PMID 33552997, 2020). "It has long been assumed that in the chronic inflammatory skin disease atopic dermatitis (AD) the expression of AMP including RNase 7 is impaired." (PMID 31749808, 2019). "Taken together, there is consistent evidence that expression of RNase 7 is induced in the skin of atopic dermatitis patients." (PMID 31749808, 2019). "Intensive staining of RNase 7 in the stratum corneum was also detected in an immunohistochemistry analysis of atopic dermatitis and psoriasis skin." (PMID 27089327, 2016). "In the case of atopic dermatitis, where S. aureus and elevated Th2 cytokines are major drivers of the disease, the capability of RNase 7 to kill S. aureus together with its influence on T cells to dampen secretion of Th2 cytokines may qualify RNase 7 as a beneficial drug to treat atopic dermatitis." (PMID 31749808, 2019). "Thus, it remains to be shown whether RNase 7 also exhibits similar immunomodulatory activities that may play a role in inflammatory diseases such as psoriasis or atopic dermatitis." (PMID 27089327, 2016). "Similarly, the ability of RNase 7 to activate an inflammatory and antiviral response in keratinocytes in the presence of self-DNA may have implications in skin diseases such as psoriasis and atopic dermatitis where self-DNA derived from injured cells may be present in increased amounts." (PMID 31749808, 2019). "Whether RNase 7 may also exhibit similar immunomodulatory activities that may play a role in psoriasis or other inflammatory skin diseases such as atopic dermatitis is not known." (PMID 27089327, 2016).
psoriasis (6 papers, 2013 to 2025). An autoimmune condition characterized by red, well-delineated plaques with silvery scales that are usually on the extensor surfaces and scalp. "Psoriasis showed a high level of expression of RNase7 in stratum corneum, but subtle expression in other layers of the epidermis." (PMID 29044786, 2018). "Furthermore, levels of RNase 7 were similar on the skin surface of lesional skin of AD and psoriasis patients." (PMID 27089327, 2016). "One may speculate that the increased amounts of RNase 7 contribute to the low infection rate seen in psoriasis." (PMID 27089327, 2016). "Thus, an enhanced production of RNase 7 may trigger inflammation in psoriasis through increased production of IFNα." (PMID 31749808, 2019). "Altogether the expression of RNase7 in PLE was significantly higher than in healthy skin or lesional skin of AD and psoriasis." (PMID 29044786, 2018). "This combination was more effective in inducing RNase 7 than the combination of IL-17A/TNF-α, a combination previously identified as a strong inducer of psoriasis-related immune response genes including several AMP." (PMID 23555696, 2013). "The increased amount of RNase 7 and other AMP in psoriasis may offer an explanation as to why psoriasis patients do not often suffer from skin infections despite the disturbed skin barrier." (PMID 31749808, 2019).
skin infection (4 papers, 2013 to 2019). An inflammatory process affecting the skin, caused by bacteria, viruses, parasites, or fungi. "This suggests that the EGFR plays an important role in cutaneous defense by its crucial role to mediate the expression of AMP such as RNase 7 and may offer an explanation for the increased susceptibility for skin infections of cancer patients receiving anti-EGFR therapy." (PMID 31749808, 2019). "In this review, we discuss how these characteristics of RNase 7 contribute to innate cutaneous defense and highlight its role in skin infection and inflammation." (PMID 31749808, 2019). "Healthy adult human skin contains a variety of pharmacological as well as functionally divergent AMPs that interact in preventing skin infections, including RNase 7, human β-defensin (HBD)-1 and psoriasin." (PMID 23545750, 2013). "The abundant constitutive expression of RNase 7 in human keratinocytes might be an important factor for the prevention of skin infections." (PMID 27089327, 2016). "Therefore, they compared 20 travelers returning with S. aureus—a positive skin infection—with a control group and documented that RNase 7 expression in unaffected skin of the control group was 64% higher than in unaffected skin of the infected individuals." (PMID 27089327, 2016). "We will discuss the peptides (defensins, cathelicidins, RNase7, dermcidin) and other mediators (toll-like receptor, IL-1 and IL-17) that comprise the host defense against S. aureus skin infection, as well as the various mechanisms by which S. aureus evades host defenses." (PMID 24840573, 2014). "The question arises whether RNase 7 may also play a role during skin infection and inflammation." (PMID 27089327, 2016). "Moreover, it can be assumed that corneocytes containing RNase 7, HBD-3 and psoriasin are trapped in the vernix and, in addition to the physical barrier, provide a further chemical barrier to prevent perinatal skin infection." (PMID 23545750, 2013).
cystitis (3 papers, 2022 to 2024). Inflammation of the urinary bladder. "Among hormones, insulin has the ability to promote the secretion of RNase 7, RNase4, and LCN2, which are proven to be against bladder infection caused by a variety of uropathogens." (PMID 36081496, 2022). "RNase 7 may be an anti-inflammatory and anti-infective mediator in bladder cells by downregulating the JAK/STAT signaling pathway and may be beneficial in treating cystitis in DM patients." (PMID 35563546, 2022). "Our findings indicate that Rnase 7 may be an anti-inflammatory and antibacterial mediator in bladder cells by downregulating the JAK/STAT signaling pathway and may be beneficial in treating cystitis in DM patients." (PMID 35563546, 2022).
Sepsis (3 papers, 2012 to 2023). Sepsis is defined as life-threatening organ dysfunction caused by a dysregulated host response to infection. "Median (IQR) concentrations of psoriasin and RNase 7 in premature and term infants after exclusion of infants with chorioamnionitis and/or sepsis." (PMID 36923410, 2023). "Median (IQR) concentrations of psoriasin and RNase 7 in premature infants after exclusion of infants with chorioamnionitis and/or sepsis." (PMID 36923410, 2023).
acne (2 papers, 2022 to 2024). An inflammatory process of the sebaceous glands which is characterized by comedones, nodules, papules and/or pustules on the skin. "Nonetheless, several AMPs share specific amino acid motifs with human endogenous AMPs, including hBDs, LL-37, dermcidin, RNAse 7, or granulysin, which may explain their anti-acne properties." (PMID 39744637, 2024).
diabetes (2 papers, 2022). "Since diabetes is known to compromise several antimicrobial peptides like hBD-1, RNase4, RNase7, and LCN2, our results are of special relevance and suggest a mode to reestablish the expression of antimicrobial peptides in type 2 diabetes patients." (PMID 34651203, 2022).
fungal infection (2 papers, 2016 to 2022). "In this work, we examined the antifungal activity of the eosinophil RNase 3 and the skin‐derived RNase 7, two proteins expressed by innate cell types that are directly involved in the host defense against fungal infection." (PMID 27277554, 2016).
staphylococcus aureus infection (2 papers, 2013 to 2024). An infectious process in which the bacteria Staphylococcus aureus is present. "It has been reported that when traveling to tropical or subtropical areas, individuals with relatively high expression levels of RNase 7 show a higher degree of resistance to Staphylococcus aureus infection of the skin compared with individuals with low levels of RNase 7 expression." (PMID 39625882, 2024). "Thus, it is intriguing to speculate that antimicrobial peptides that exhibit anti-staphylococcal activity and are regulated via STAT3 such as RNase 7 may be dysregulated in keratinocytes of HIES patients which may contribute to frequent Staphylococcus aureus infections." (PMID 23555696, 2013).
urinary tract infection (2 papers, 2022 to 2023). "This is of particular interest as, for example, in adult patients, reduced RNase 7 concentrations in urines are associated with a higher risk for urinary tract infections." (PMID 36923410, 2023).
viral infection (2 papers, 2011 to 2020). "This category contained the nucleases RNASE7, RNASEH2A, RNASE10, and EXO1, as well as proteins regulating nucleases, like the OAS-protein family that are known to activate RNase L activity upon viral infection." (PMID 32545414, 2020). "We focused on the antimicrobialmolecule RNASE7, a member of the RNase A superfamily with broad-spectrumantimicrobial activity and ribonuclease activity, which was not known to beaffected by viral infection." (PMID 21423754, 2011).
Acanthamoeba keratitis (1 paper, 2022). Keratitis due to infection by acanthamoeba; it is usually associated with soft contact lens wear, particularly overnight wear. "Further studies have demonstrated elevated levels of RNase-7 in samples collected from patients with bacterial, viral and Acanthamoeba keratitis as well as in CECs treated with cytokines, live bacteria and different pathogenic proteins that activates innate immune receptor signaling." (PMID 35783647, 2022). "Similarly in Acanthamoeba keratitis, a wide range of HDPs such as HBD-2 and−3, LL-37, LEAP-1 and−2, and RNase-7 (but not HBD-1), were shown to be upregulated." (PMID 35783647, 2022).
acute pyelonephritis (1 paper, 2023). "During acute pyelonephritis, the concentration of RNase 7 doubles as a front-line response against uropathogens." (PMID 36983379, 2023). "RNase 7 activity is regulated by its interaction with ribonuclease inhibitors, as well as expression and activity of the latter, decreasing in acute pyelonephritis." (PMID 36983379, 2023).
cholesteatoma (1 paper, 2014). A pathologic process characterized by the proliferation of keratinizing squamous epithelium resulting in the accumulation of keratin and cells in the middle ear and/or mastoid. "All proteins, except RNASE7, showed increased expression in both cholesteatoma and neck of cholesteatoma, and showed significant overlaps with the biological process "response to bacteria" and the molecular function "endopeptidase activity" according to the STRING analysis." (PMID 25093596, 2014).
corneal infection (1 paper, 2019). A viral or bacterial infectious process affecting the cornea. "We determined the expression pattern of AMPs elicited in corneal infections caused by S. pneumoniae in patients for the first time, and we found significantly increased expressions of hBD2 and 3, S100A8, S100A9, S100A12, LL-37, lipocalin, Rnase7, and hepcidin." (PMID 30845777, 2019).
Dengue virus infection (1 paper, 2015). "Interestingly, the antiviral role of RNase 7 was previously reported but in the context of Dengue virus infection." (PMID 26091527, 2015).
gram-negative bacterial infections (1 paper, 2022). Infections caused by bacteria that show up as pink (negative) when treated by the gram-staining method. "The rapid and powerful antibacterial effect of RNase 7 in Gram-positive and Gram-negative bacterial infections is caused by the breakdown of cell membranes." (PMID 35563546, 2022). "AMPs in the urinary tract include defensins, cathelicidin, hepcidin, and RNase 7, an enzyme with antimicrobial properties that has rapid and powerful antibacterial effects against Gram-positive and Gram-negative bacterial infections." (PMID 35563546, 2022). "RNase 7 with antimicrobial properties has rapid and powerful suppressive effects against Gram-positive and Gram-negative bacterial infections." (PMID 35563546, 2022).
gram-positive bacterial infections (1 paper, 2013). Infections caused by bacteria that retain the crystal violet stain (positive) when treated by the gram-staining method. "In contrast, the expression of IL-6 and RNAse7 was dependent on the presence of MRSA, while previously it was reported that RNAse7 expression was not induced by a gram-positive bacterial infection (e.g. with S. aureus)." (PMID 24340061, 2013).
inflammatory skin disease (1 paper, 2019). Inflammatory skin disorders covers a broad category that includes many conditions ranging in severity, from mild itching to grave medical health complications These disorders are common in people of all ages and races. "We also speculate how a potential dysregulation of RNase 7 promotes inflammatory skin diseases and if RNase 7 may have therapeutic potential." (PMID 31749808, 2019).
lung carcinoma (1 paper, 2020). "The mechanism and function of RNASE7, and ELN had not been reported in lung cancer." (PMID 32699529, 2020).
Parkinson’s (1 paper, 2022). "RNASE7 is a public differentially expressed gene that was in a previously reported set of DEGs in Parkinson’s patients’ skin." (PMID 36292747, 2022).
peritonitis (1 paper, 2019). Inflammation of the peritoneum (tissue that lines the abdominal wall and covers most of the organs in the abdomen). "The potential links between RNase 7 levels, patient age, mesothelial content, and peritonitis susceptibility warrant additional investigation." (PMID 31123272, 2019). "The areas under the receiver-operating characteristic curves for RNase 3 and RNase 7 were 0.99 (95% confidence interval (CI): 0.96–1.0) and 0.79 (95% CI: 0.64–0.93), respectively, indicating their potential as biomarkers of peritonitis." (PMID 31123272, 2019). "The areas under the ROC curves for RNase 7 and particularly RNase 3 predict that they are good to excellent candidate biomarkers of peritonitis." (PMID 31123272, 2019). "During peritonitis, RNase 3 increased 55-fold and RNase 7 levels increased 3-fold on average, whereas RNase 6 levels were unchanged." (PMID 31123272, 2019). "Peritoneal fluid concentrations of RNase 3 and RNase 7 increase during peritonitis, and further studies are warranted to test their efficacy as peritonitis biomarkers." (PMID 31123272, 2019). "Further, larger scale studies are required to determine whether the addition of RNase 3 and RNase 7 measurement to standard evaluation methods increases the sensitivity and specificity of peritonitis diagnosis in the chronic PD patient population." (PMID 31123272, 2019). "During peritonitis, we observed accumulation of RNase 3 and RNase 7 in peritoneal fluid." (PMID 31123272, 2019). "In the absence of peritonitis, we detected RNase 3, RNase 6, and RNase 7 in cell-free supernatants and viable cells obtained from peritoneal fluid of chronic PD patients." (PMID 31123272, 2019). "In this study, we demonstrated the presence of RNase 3, RNase 6, and RNase 7 in the peritoneal fluid of patients receiving chronic PD who lacked clinical signs and symptoms of peritonitis." (PMID 31123272, 2019). "RNase 7 levels increased 3-fold on average (range 1–19), from a median value of 2071 pg/ml (IQR 1592–4628) in uninfected fluid to 6692 pg/ml (IQR 3080–8805) in adults with peritonitis." (PMID 31123272, 2019). "Mesothelial loss as a consequence of chronic PD may account for absent induction of RNase 7 in certain patients with peritonitis." (PMID 31123272, 2019).
pyelonephritis (1 paper, 2014). An inflammatory process affecting the kidney. "RNase7 is important in the urinary tract due to the observation of an increase in levels in urine samples obtained from patients with pyelonephritis as compared to healthy controls." (PMID 26029470, 2014). "While RNase7 is significantly increased in relation to RNase6 in non-infected human bladder and kidney tissues, RNase6 expression significantly increases during pyelonephritis due to the influx of immune cells." (PMID 26029470, 2014).
tinea (1 paper, 2014). "Recently, it has been reported that AMP are induced in the lesional epidermis of tinea patients and that the skin-derived AMP psoriasin, hBD-2 and RNase 7 are able to inhibit the growth of dermatophytes in vitro." (PMID 24747887, 2014).